DSG2 (desmoglein 2)
Diseases named in the same sentence as DSG2 in open-access papers (continued):
Sharing a sentence is not in itself a finding about the gene and the disease.
melanoma (continued). "Moreover, the level of DSG2 mRNA was significantly increased in this subset of patients compared to samples without amplification, suggesting CNV as one possible mechanism contributing to DSG2 up-regulation in melanoma, although non-genetic mechanisms are also clearly involved." (PMID 27340778, 2016).
squamous cell carcinoma (18 papers, 2013 to 2024). A carcinoma arising from squamous epithelial cells. "In the context of squamous cell carcinoma, Desmoglein 2 (Dsg2) has been implicated in the promotion of tumor growth via an EV-mediated mechanism." (PMID 39796048, 2024). "DSG2 was low expression in gastric cancer, squamous cell carcinoma, lung cancer and prostate cancer." (PMID 33407183, 2021). "DSG3 is overexpressed in squamous cell carcinoma and head and neck cancer, and abnormal expression of DSG2 in melanoma, squamous cell carcinoma, and gastric cancer has also been reported." (PMID 32498335, 2020). "Basal cell carcinomas, squamous carcinomas and prostate carcinoma cells with high metastatic potential contain increased amounts of Dsg2 whereas in certain types of gastric carcinomas Dsg2 is reduced or abnormally distributed." (PMID 24558503, 2014). "The reduction of Dsg2 on the squamous cell carcinoma membrane increased the release of extracellular vesicles (EVs) containing EGFR and Src and that these EVs containing EGFR and Src can modulate the tumor microenvironment, a step critical for tumor progression." (PMID 32989241, 2021). "The Desmoglein 2 (DSG2) gene is located at 18q12.1, and the encoded protein is a calcium‐dependent desmosomal cadherin, which is abnormally expressed in a variety of tumor tissues, such as breast cancer, squamous cell carcinoma, and non‐small cell lung cancer." (PMID 32997416, 2020). "Moreover, overexpression of DSG2 in lung adenocarcinoma and squamous cell carcinoma cells activates EGFR and increases cancer cell proliferation and migration by c‐Src and EGFR‐dependent manner." (PMID 32997416, 2020). "Furthermore, DSG2 regulates the release of extracellular vesicles of squamous cell carcinoma keratinocytes and regulates the tumor microenvironment by this mechanism." (PMID 32997416, 2020). "Dsg2 is up-regulated in many epithelial-derived tumors such as basal and squamous cell carcinomas." (PMID 25785582, 2015). "Interestingly, a role for DSG2 in exosomes and cancer progression has been identified in squamous cell carcinoma with DSG2 promoting the secretion of exosomes that contain pro‐mitogenic cargo such as IL‐6, a known contributor to myeloma development and progression." (PMID 34245117, 2022). "As an example, squamous cell carcinoma (SCC) derived EVs, with enhanced desmoglein 2 (Dsg2) expression, have been shown to promote cancer pathogenesis via targeting survival pathways and TME." (PMID 33291683, 2020). "The role of Dsg2 in tumorigenesis emerged with the findings that Dsg2 expression is highly upregulated in several epithelial-derived malignancies including basal cell carcinomas (BCC) and squamous cell carcinomas (SCC)." (PMID 25871385, 2015). "Taken together, Dsg2 mAb in contrast to AK23 did not reduce cell-cell adhesion in a human keratinocyte cell line as well as the squamous carcinoma cell line SCC9, whereas it was readily impairing monolayer integrity in cells expressing Dsg2 as the only Dsg isoform." (PMID 23326495, 2013).
breast carcinoma (17 papers, 2019 to 2025). "Their binding to the DSG2 promoter results in sustained DSG2 repression, a process correlated with poor prognosis and increased recurrence risk, particularly in breast cancer patients." (PMID 40507913, 2025). "DSG2 is an important cell-cell adhesion molecule associated with poor prognosis and tumor growth in breast cancer patients." (PMID 38798352, 2024). "Recently, the desmosomal protein desmoglein 2 (DSG2) has been associated with a poorer prognosis and higher recurrence risk in breast cancer patients." (PMID 36927383, 2023). "DSG2 has been associated with a poor prognosis and increased recurrence risk in breast cancer patients and is linked to an increased metastatic potential of breast cancer cells by promoting cell clustering and enhancing cell survival during tumor cell dissemination." (PMID 38539508, 2024). "In a cohort of ten patients with breast cancer with distant metastasis, we observed higher expression of DSG2 and PG in tumor tissues compared to adjacent normal tissues." (PMID 41381723, 2025). "Hirudin inhibits hematogenous metastasis of breast cancer through suppression of HIF-1α-controlled DSG2-mediated desmosome junctions, ultimately leading to the disintegration of CTC clusters." (PMID 41381723, 2025). "The improved infectivity of Ad5/3 chimeric fiber, which recognizes Ad3 receptors (CD46 and DSG2), was demonstrated in different cancer models, including breast cancer, glioma, esophageal adenocarcinoma, and pancreatic cancer." (PMID 38675909, 2024). "DSG2 has also been reported to be regulated by Hypoxia-inducible factor 1 (HIF1)-α to support metastasis in breast cancer." (PMID 38188287, 2023). "DSG2 expression is regulated by hypoxia in breast cancer cells and increases the prevalence of CTC clusters, facilitating distant metastasis." (PMID 36927383, 2023). "Desmoglein 2, desmocollin 2 (DSC2) and plakophilin 1 (PKP1) have been recently linked to an increased metastatic potential of breast cancer cells by promoting cell clustering and enhanced survival during the tumour cell dissemination process." (PMID 36927383, 2023). "DSG2 pretreated breast cancer cells have decreased cell aggregation, increased invasion, and motility in vitro." (PMID 32997416, 2020). "Reportedly, the recombinant adenovirus serotype 3-derived protein (JO-1), which triggers the transient opening of intercellular junctions in epithelial tumors by binding to DSG2, enhanced the antitumor activity of several therapeutic monoclonal antibodies in breast cancer, lung cancer, and GC." (PMID 32774771, 2020). "DSG2 present in breast cancer cells may function as a tumor suppressor molecule." (PMID 32095325, 2020). "Our findings highlight the therapeutic potential of targeting HIF-1α-controlled DSG2-mediated desmosome junction conversion and position hirudin as a promising CTC clusters dissociator optimized for the clinical prevention of breast cancer metastasis." (PMID 41381723, 2025). "Similar with our findings, serval studies have demonstrated EPS8, DSG2, ITGB6 were aberrantly expressed in pancreatic cancer, breast cancer, pituitary tumor, and gastric cancer." (PMID 36237305, 2022). "When the DSG2 was first identified in 2011, it was observed that Pt-Dd binding to DSG2 triggered an epithelial-to-mesenchymal transition (EMT) on breast cancer cells (B474), leading to transient opening of intercellular junctions." (PMID 32630840, 2020). "While elucidating the mechanism by which hirudin inhibits breast cancer metastasis, our findings indicate that HIF-1α and DSG2 may serve as potential targets for the development of CTC cluster dissociation agents." (PMID 41381723, 2025). "We further revealed that the HIF-1α–DSG2 axis mediates conversion between desmosome and adhesion junctions in CTC clusters, which is crucial for CTC cluster formation and disintegration during breast cancer metastasis." (PMID 41381723, 2025).
breast carcinoma (continued). "Applying label-free proteomic quantitation method and statistical analysis, several differentially expressed proteins (DEPs) were identified in the serum of breast cancer patients compared to controls, including SBSN, ANG, PCOLCE, and WFDC3 (upregulated), and PFN1, FLNA, and DSG2 (downregulated)." (PMID 39990193, 2024).
lung cancer (17 papers, 2013 to 2026). A malignant neoplasm involving the lung. "DSG2 mRNA expression can be restored by demethylation treatment in some of the lung cancer cell lines." (PMID 32850288, 2020). "Previously it has been shown that Ad3 infection of A549 lung cancer cells and human 16HBE14o bronchial cells were mainly mediated via binding with DSG2 and only about 10% occurred via the CD46 receptor, which supports our results." (PMID 31944306, 2020). "Taken together, increased levels of CAR and DSG2 could help target oncolytic adenovirus vectors for use as a therapeutic tool in lung cancer; however, they also appear to indicate inferior survival outcomes in NSCLC." (PMID 33217893, 2020). "DSG2 was also highly detected in primary lung cancers, especially in LSCC." (PMID 33217893, 2020). "TMA also showed that CAR/DSG2 expressions were altered in lung cancer tissue." (PMID 33217893, 2020). "Importantly, the functional importance of DSG2/Siglec‐9 interaction could be replicated in lung cancer and cervical cancer cell lines with high DSG2 expressions, suggesting DSG2 might be a potential target in cancer immunotherapy." (PMID 39813162, 2025). "It has been reported by us and others that DSG2 promotes cancer cell migration, invasion, and proliferation in cancers such as SCC, breast, cervical, colon, and lung cancer." (PMID 38188287, 2023). "Unlike lung cancer, the role of DSG2 in digestive cancers was not well defined and previous reports were even paradoxical." (PMID 35345582, 2022). "Cleavage of DSG2 was mediated by junction opener 1 (JO-1), and downstream signaling combined with a monoclonal antibody targeting EGFR, Erbitux, provide better therapeutic outcomes in EGFR-positive lung cancer." (PMID 24369726, 2013).
pancreatic cancer (16 papers, 2008 to 2025). "In pancreatic cancer cells, loss of DSG2 promoted a pro-migratory behavior, which was dependent on ERK signaling and expression of PG17." (PMID 39107343, 2024). "Vishnu C Ramani’s study showed that DSG2 expression was reduced in pancreatic tumors, and it suggested that loss of desmosomal proteins play an important role in pancreatic cancer invasion." (PMID 33407183, 2021). "The correspondence between increased hK7 expression in pancreatic tumors and loss of Dsg2 is highlighted in the immunohistochemistry studies we have performed." (PMID 19091121, 2008). "Thus, loss of a desmosomal protein such as DSG2 or DP induced phosphorylation of ERK1/2 in cardiac myocytes or in a pancreatic cancer cell line." (PMID 32556797, 2020). "A reduction in the amount of the cell adhesion components DSG1 and DSG2 in pancreatic tumours suggests that loss of these desmosome proteins may play a role in pancreatic cancer invasion." (PMID 32850288, 2020). "A reduction in the amount of the cell adhesion components Dsg1 and Dsg2 in pancreatic tumors suggests that loss of these desmosomal proteins may play a role in pancreatic cancer invasion." (PMID 19091121, 2008). "Here, we investigated the contribution of the desmosomal core adhesion molecule desmoglein-2 (DSG2) to the initial steps of liver metastasis formation by pancreatic cancer cells using a novel ex vivo liver perfusion mouse model." (PMID 39107343, 2024). "In summary, this study highlights the relevance of DSG2 and desmosomal function for pancreatic tumor cell cluster formation and the initial phase of metastatic spreading to the liver." (PMID 39107343, 2024). "The CAR and DSG2 gene underexpression is reported in pancreatic cancer cells, due to the high expression of MEK and ERK." (PMID 35359382, 2022). "For the positive control, the interaction pattern of CAR and DSG2 with the HAdV2, HAdV3, and HAdV5 L5 proteins is analyzed and compared with pancreatic cancer receptors." (PMID 35359382, 2022). "For example, DSG2 is over-expressed in malignant skin carcinomas and low-expressed in pancreatic cancer (Ramani, Hennings & Haun, 2008)." (PMID 32095325, 2020). "On the contrary, an elevated level of desmoglein-2 in spheroids of pancreatic cancer cells compared to monolayer culture was reported, which also led to increased resistance to doxorubicin." (PMID 33291824, 2020). "Downregulation of DSG-2 in pancreatic cancer decreased cell–cell contacts and increased cell invasion, promoting metastasis." (PMID 32957644, 2020). "With both Dsg1 and Dsg2, there was a pronounced shift toward the lower intensity categories in the pancreatic cancer samples." (PMID 19091121, 2008). "The expression of Dsg1, Dsg2, and Dsg3 in pancreatic tissues was examined by immunohistochemistry and their expression in two pancreatic cancer cell lines, BxPC-3 and Panc-1, was determined by western blot analysis." (PMID 19091121, 2008). "This supports the hypothesis that reduced initial attachment of DSG2 KO cells translates into reduced metastasis formation which is in line with increased survival of patients with low DSG2-expressing pancreatic tumors." (PMID 39107343, 2024). "We established and validated a telomere gene-related prognostic signature for pancreatic cancer and confirmed the upregulation of DSG2, LDHA, and RACGAP1 expression in clinical samples, which may provide new ideas for individualized immunotherapy." (PMID 37391503, 2023). "Similarly, DSC2, DSG2, and LAMA3 were also found to be highly expressed and significantly associated with poor prognosis in pancreatic cancer." (PMID 35570408, 2022). "This decrease in DSG-2 expression might be mediated by a protease, kallikrein 7, which is upregulated in pancreatic cancer." (PMID 32957644, 2020). "Additionally, downregulation of DSG-2 has been observed in gastric cancer, malignant ovarian tumors, and pancreatic cancer." (PMID 32957644, 2020).
pancreatic cancer (continued). "Thus, the ability of hK7 to degrade desmogleins was assessed and the effect of hK7 expression on desmoglein 2 was examined in cultured pancreatic cancer cells." (PMID 19091121, 2008). "We established and validated telomere gene-related prognostic features in pancreatic cancer and confirmed the upregulation of DSG2, LDHA, and RACGAP1 expression in clinical samples, which may provide new ideas for individualized immunotherapy targeting telomere genes." (PMID 37391503, 2023). "All the pancreatic cancer samples displayed an intense desmoplastic response, the synthesis and deposition of collagenous material by stromal myofibroblasts surrounding the adenocarcinoma, and the membrane staining for both Dsg1 and Dsg2 was distinctly weaker in most of the cancer samples analyzed." (PMID 19091121, 2008). "We also found that high levels of DSG2, LDHA, and RACGAP1 predicted poorer overall and disease-free survival in pancreatic cancer patients, although these three genes did not all show good performance in the four validation datasets." (PMID 37391503, 2023). "An extracellular fragment of DSG2 can be shed from the cell surface via MMP9 and ADAM17 and has been documented to be elevated in the serum of patients with pancreatic cancer." (PMID 34245117, 2022). "We tested the murine ex vivo model using the pancreatic cancer cell line AsPC-1 with and without expression of the core desmosomal adhesion molecule DSG2." (PMID 39107343, 2024). "Finally, we also found that protein levels of DSG2, LDHA, and RACGAP1 were upregulated in pancreatic cancer tissues compared to normal tissues by immunohistochemistry analysis." (PMID 37391503, 2023). "Although the percentage of cells lacking demonstrable Dsg2 staining (0+) increased with the severity of disease (i.e., pancreatic cancer > chronic pancreatitis > normal pancreas), the numbers were modest in all three tissue types." (PMID 19091121, 2008).
heart failure (13 papers, 2017 to 2026). Inability of the heart to pump blood at an adequate rate to meet tissue metabolic requirements. "PKP2 variants are associated with more arrhythmias and classical RV-dominant ACM while desmoplakin (DSP) and desmoglein-2 (DSG2) pathogenic variants are associated with more heart failure." (PMID 38137480, 2023). "These epidemiologic data combined with our findings suggest that desmoglein-2 deficiency might be concealed among the genetically undiagnosed idiopathic DCM patients with severe heart failure." (PMID 33949662, 2021). "They found that the DSG2 variant might contribute to heart failure by affecting desmosomes.The results suggest that the DSG2 p.Arg119Ter variant is more common in East Asian populations and may worsen heart conditions when combined with other genetic or environmental factors." (PMID 39706847, 2024). "Loss or mutation of the desmoglein 2 gene (Dsg2) results in arrhythmogenic cardiomyopathy (AC), which is characterized by impaired cardiomyocyte coupling, aseptic inflammation and fibrofatty tissue replacement ultimately leading to heart failure in human patients and animal models." (PMID 34737300, 2021). "Arrhythmogenic cardiomyopathy (ACM) is a genetic form of heart failure that affects 1 in 5,000 people globally and is caused by mutations in cardiac desmosomal genes including PKP2, DSP, and DSG2." (PMID 42090754, 2026). "Arrhythmogenic cardiomyopathy (ACM) is a genetic form of heart failure that affects 1 in 5000 people globally and is caused by mutations in cardiac desmosomal proteins including PKP2, DSP, and DSG2." (PMID 39763850, 2024). "In the present study, PKP2, DSG2, and DSC2-KOs experiment with a decrease in ATPase expression (codified for SERCA), indicating that the absence of those genes may be linked to heart failure, a clinical feature present in ACM phenotype." (PMID 36768439, 2023).